PIM1 (Pim-1 proto-oncogene, serine/threonine kinase)
Diseases named in the same sentence as PIM1 in open-access papers (continued):
Sharing a sentence is not in itself a finding about the gene and the disease.
lung adenocarcinoma (8 papers, 2016 to 2025). A carcinoma that arises from the lung and is characterized by the presence of malignant glandular epithelial cells. "A sub-analysis of lung adenocarcinoma cases only indicates a significant association between PIM1 mRNA expression and reduced overall survival (n = 719 HR = 1.39, p = 0.0098)." (PMID 33946744, 2021). "It is reported that PIM1 expression is closely related to lymph node metastasis and poor prognosis in lung adenocarcinoma and squamous cell carcinoma patients." (PMID 35672846, 2022). "For example, PIM1 acts as an oncogenic gene in lung adenocarcinoma and promotes tumor growth by activating the c-mesenchymal to epithelial transition factor signaling pathway." (PMID 34519263, 2021). "To establish the clinical relevance of increased PIM1/GSK3β signaling in mediating acquired resistance to osimertinib in NSCLC, we obtained CT images of three cases of advanced EGFR-mutant lung adenocarcinoma." (PMID 39227379, 2024). "In addition, analysis of expression data of lung adenocarcinoma (LUAD) and 26 non-LUAD tumors in TCGA suggests that LUAD patients tend to express higher levels of PIM1 mRNA (student t test p < 2.2e–6)." (PMID 26916442, 2016).
colorectal cancer (7 papers, 2017 to 2024). A primary or metastatic malignant neoplasm that affects the colon or rectum. "As demonstrated in the tissue of colorectal cancer patients, higher expression of PIM1 was associated with the degree of local invasion and lymph node metastasis." (PMID 32521759, 2020). "Provirus integration site for Moloney murine leukemia virus (Pim1) is linked to the development and progression of several cancers including colorectal cancer." (PMID 28160571, 2017). "Previous studies have indicated that hispidulin inhibits the Janus kinase 2 (JAK2)/STAT3 pathway by generating ROS in colorectal cancer cells, and downregulates the expression of the oncogene PIM1." (PMID 34356663, 2021). "In vitro cell-based assays on human hematologic (AML) and solid tumor (colorectal carcinoma) cell lines overexpressing Pim-1/2 kinases were then realized, showing growth inhibitory activities at micromolar concentrations." (PMID 33562106, 2021). "These molecules were also able to inhibit the growth of the two human cell lines, MV4-11 (AML) and HCT-116 (colorectal carcinoma), expressing high endogenous levels of Pim-1/2 kinases." (PMID 33562106, 2021). "Hispidulin inhibited growth and metastasis of HT29 and SW480 colorectal cancer cells in vitro by targeting of PIM1 through inhibition of JAK2/STAT3 signaling by generating reactive oxygen species." (PMID 32521759, 2020). "Some top-ranked candidates were PIM1 in bladder cancer (FDR ≈ 1%), ZFHX4 in colorectal cancer (FDR ≈ 1%), ERBB2 in prostate, stomach, breast luminal subtype, and bladder cancers (FDR ranging from 4% to 14%) and others." (PMID 39033140, 2024).
glioblastoma (7 papers, 2013 to 2025). The most malignant astrocytic tumor (WHO grade IV). "The proto-oncogenic survival kinase Pim1 is overexpressed in glioblastoma and has been associated with tumor cell survival, proliferation and anti-apoptotic effects." (PMID 32967361, 2020). "In the context of glioblastoma, PIM1 inhibition is expected to lead to tumor growth suppression, cell cycle arrest, and promotion of apoptosis in cancer cells." (PMID 41009025, 2025). "Our results indicate that PIM1 affects the glioblastoma stem cell behavior, and its inhibition kills glioblastoma stem-like cells, pointing to PIM1 targeting as a potential anti-glioblastoma therapy." (PMID 34681783, 2021). "Similarly, PIM1-U1i adaptors, encapsulated within nanoparticles and injected intratumorally into glioblastoma xenografts, reduced tumor growth by 40–50%, compared to controls." (PMID 24285958, 2013). "The functional relationship between PIM1 and cancer has been well established in recent years, but there is limited knowledge of its precise role in glioblastoma (GBM) and, in particular, GBM stem cell behavior." (PMID 34681783, 2021).
glioma (7 papers, 2017 to 2021). A benign or malignant brain and spinal cord tumor that arises from glial cells (astrocytes, oligodendrocytes, ependymal cells). "Compared with the shRNA control, knockdown of TRIM59 significantly inhibited p-STAT3, PIM1 mRNA expression, glioma sphere formation, and tumorigenicity of intracranial xenografts, but increased mH2A1 protein levels." (PMID 31488827, 2019). "Re-expression of shRNA-resistant TRIM59 WT or S308D mutant rescued p-STAT3, PIM1 mRNA expression, glioma sphere formation, and tumorigenesis of intracranial xenografts, but inhibited mH2A1 protein levels." (PMID 31488827, 2019). "Both erlotinib and Roscovitine treatments markedly inhibited TRIM59 nuclear translocation, p-STAT3, PIM1 mRNA expression, and glioma sphere formation, but increased mH2A1 protein levels, validating our observations in LN229/EGFR GBM cells." (PMID 31488827, 2019). "Moreover, the lncRNA, KCNQ1OT1, was reported to confer chemoresistance in gliomas via sponging miR-761 and subsequently upregulating peripheral interface module 1 (PIM1)." (PMID 34268119, 2021). "However, knockdown of PIM1 by siRNA revealed a strong reduction of the two most widely accepted glioma stem cell markers, CD133 and Nestin." (PMID 34681783, 2021). "KCNQ1OT1 C by retrieving PIM1 FrommiR-761 could confer gliomas resistance to TMZ." (PMID 34178658, 2021). "MiR-124-3p restoration represses the migration and/or invasion of glioma cells by targeting Capn4, IQGAP1, iASPP, and PIM1." (PMID 31708690, 2019). "Moreover, restoration of miR-124a could inhibit glioma cell proliferation and invasion through miR-124a blocking the expression of the IQGAP1 gene and downstream β-catenin and cyclin D1 and PIM1 in astrocytoma cancer cells." (PMID 29138748, 2017).
prostatic intraepithelial neoplasia (7 papers, 2010 to 2023). "PIM1 levels are elevated in high-grade prostatic intraepithelial neoplasia relative to normal tissue and further elevated in castration-resistant prostate cancer, and high PIM1 expression is associated with resistance to therapy." (PMID 37042842, 2023). "PIM1 has been previously found to have increased expression in high grade prostatic intraepithelial neoplasia and PCa in comparison to normal prostate tissues." (PMID 28947967, 2017). "We found that pim1 overexpression moderately increased the severity of mouse prostate intraepithelial neoplasia (mPIN) in all three settings." (PMID 24860787, 2014). "We have found that Pim1 overexpression increased the severity of mouse prostate intraepithelial neoplasias (mPIN) moderately in all three settings." (PMID 23565217, 2013).
diabetes (6 papers, 2014 to 2025). "In the current study, we found that Pim-1 was downregulated within 4 weeks of STZ-induced diabetes in the female heart, which was associated with increased pro-apoptotic caspase-3 expression." (PMID 24685144, 2014). "Accumulating evidence suggests that Pim1 exerts protective effects on diabetes-induced myocardial injury and is down-regulated in diabetic hearts." (PMID 39850120, 2025). "Our earlier studies showed significant downregulation of the pro-survival protein Pim-1 in the male diabetic heart at 8 weeks after the onset of STZ-induced diabetes." (PMID 24685144, 2014). "Additionally, benfotiamine was previously demonstrated to improve diastolic dysfunction in diabetes-induced heart failure via activation of Akt/Pim-1-mediated survival pathway." (PMID 32384080, 2020). "Interestingly, upregulation of Pim-1 expression was observed in both STZ-induced diabetes and HG-treated VSMCs." (PMID 29179437, 2017).
neuroblastoma (6 papers, 2019 to 2023). Neuroblastoma (NB) is the most common solid, extracranial childhood tumor. "In support of this assertion, mitochondrial fission can induce PIM1 expression and trigger glycolytic metabolism in human small airway epithelial cells, similar to the effects of Survivin in aggressive neuroblastoma cells." (PMID 37414143, 2023). "In their review of the Kocak dataset (Gene Expression Omnibus GSE45547, n = 476), they found high expression of either PIM1, PIM2, or PIM3 mRNA to be significantly associated with poor overall survival in neuroblastoma." (PMID 35892829, 2022). "The siRNA knockdown of PIM1 reduced the viability of two neuroblastoma cell lines, KELLY and SH-SY5Y." (PMID 35892829, 2022). "They demonstrated that PIM1-mediated ALK inhibitor resistance occurred through the phosphorylation of BAD, resulting in decreased neuroblastoma apoptosis." (PMID 35892829, 2022). "PIM1, on the other hand, is the PIM kinase most extensively studied in neuroblastoma and osteosarcoma." (PMID 35892829, 2022). "Genome-wide CRISPR activation screens of neuroblastoma cells treated with ALK inhibitors brigatinib or ceritinib for 14 days identified Pim1 as a resistance gene, due to an anti-apoptotic phosphorylation of BAD by PIM1." (PMID 37414143, 2023). "PIM1 and PIM3 were expressed in neuroblastoma cell lines and PDX‐derived cell cultures." (PMID 31310053, 2019).
pulmonary arterial hypertension (6 papers, 2017 to 2025). Pulmonary arterial hypertension (PAH) is a group of diseases characterized by mean pulmonary artery pressure >20 mmHg and elevated pulmonary arterial resistance leading to right heart failure. "Serine/threonine kinase proviral integration site for Moloney murine leukemia virus 1 (Pim-1) plays an essential role in arterial wall cell proliferation and associated vascular diseases, including pulmonary arterial hypertension and aortic wall neointima formation." (PMID 29179437, 2017). "Pim-1 is increased 11-fold in coronary artery disease, present in pulmonary arterial hypertension, and Pim-2 is upregulated in atherosclerotic arteries in coronary artery disease." (PMID 37511341, 2023). "Pim-1 is an oncoprotein that is overexpressed in the lungs of patients with pulmonary arterial hypertension (PAH) and is involved in cell proliferation by activating the nuclear factor of the activated T cells (NFAT)/STAT3 signaling pathway." (PMID 36036015, 2022). "Indeed, PIM1 has been reported as a marker for pulmonary hypertension." (PMID 39723205, 2024).
viral infection (6 papers, 2018 to 2023). "PIM1 is a serine/threonine-protein kinase found to be involved in the pathogenesis of several viral infections." (PMID 37211584, 2023). "PIM1 was also reported to be involved in host response to many viral infections, such as hepatitis B, Epstein-Barr, and human papilloma viral infections." (PMID 37211584, 2023). "Meanwhile, miR-542, miR-486 and miR-124-3p were reported to target PIM1, as well as hypoxia and virus infection." (PMID 30989585, 2019). "Second, it has been reported that inhibition of PIM1 with an inhibitor suppressed viral infection, postulating the possibility that PIM1 is involved in innate immune response." (PMID 29427062, 2018). "Hence, targeting PIM1 using PIM1 inhibitors could be effective in combating virus infection." (PMID 37211584, 2023). "Thus, although our RLR or cGAS findings remain to be confirmed and extended with analyses of kinase-deficient Pim1, they tentatively suggest that targeting the kinase-independent interaction between Pim1 and the IRF3 signaling complex could help control viral infections." (PMID 36446848, 2022).
acute lymphoblastic leukemia (5 papers, 2012 to 2023). Leukemia with an acute onset, characterized by the presence of lymphoblasts in the bone marrow and the peripheral blood. "We demonstrate that the PIM1 protein kinase induces the long noncoding RNA (lncRNA) H19 expression and promotes induction of a stem cell signature in both T‐cell acute lymphoblastic leukemia (T‐ALL) and PCa cells." (PMID 32146726, 2020). "Some T-cell-driven hematological cancers, such as T-cell acute lymphoblastic leukemia (T-ALL) and T-cell acute lymphoblastic lymphoma (T-LBL), have been shown to have increased PIM1 activity, suggesting the potential of PIM1 as a therapeutic target in these cancers." (PMID 36429128, 2022).
CNS lymphomas (5 papers, 2022 to 2024). "Moreover, MYD88, CD79B, and PIM1 mutations were commonly found in primary CNS lymphomas and DLBCLs with CNS relapse." (PMID 36081566, 2022). "In another subtype of NHL, primary central nervous system lymphoma (PCNSL), Pim-1 is one of the most highly mutated genes and over 77% of PCNSL harbored Pim1 mutations." (PMID 36694243, 2023). "PCLBCL, LT showed highly recurrent mutations of MYD88 (p.L265P variant), PIM1, and CD79B, which are involved in the NF-κB and B-cell receptor signaling pathways, similar to primary central nervous system lymphoma (PCNSL)." (PMID 35452489, 2022). "Gene alterations in BTG2, PIM1, DUSP2, ETV6 and CXCR4 had been identified in more than 20% of patients with primary CNS lymphoma (PCNSL) in a study by Wang and colleagues." (PMID 38173015, 2024).
mantle cell lymphoma (5 papers, 2012 to 2023). Mantle cell lymphoma is a rare form of malignant non-Hodgkin lymphoma affecting B lymphocytes in the lymph nodes in a region called the ``mantle zone''. "Further evidence for these processes have been demonstrated in mantle cell lymphoma (MCL), where immunoblotting has found that oncogenic mRNA encoding cell proliferation factors such as Cyclin D1, PIM-1, and c-Myc are indeed exported via XPO1." (PMID 36671496, 2023). "In mantle cell lymphoma, PIM-1 and Ki67 expression were predictive of poorer outcomes in a Phase II clinical trial of aggressive chemotherapy and rituximab." (PMID 23115625, 2012). "Both PIM1 and PIM2 mRNAs are highly expressed in CLL, DLBCL and mantle cell lymphoma (MCL), whereas PIM2 is also overexpressed in follicular lymphoma, MALT lymphoma, nodal marginal zone lymphoma and multiple myeloma." (PMID 26643319, 2015).
non-small cell lung carcinoma (5 papers, 2012 to 2020). A group of at least three distinct histological types of lung cancer, including non-small cell squamous cell carcinoma, adenocarcinoma, and large cell carcinoma. "Similarly, depletion of Pim1, 2 and 3 by siRNAs in non-small cell lung carcinoma cell line (A549) and a cervical cancer cell line (HeLa) abolished phosphorylation of IRS proteins on S1101." (PMID 26956053, 2016).
rheumatoid arthritis (5 papers, 2020 to 2024). A chronic, systemic autoimmune disorder characterized by inflammation in the synovial membranes and articular surfaces. "We highlight six tocilizumab responsive genes (ARID5A, BCL3, PIM1, SOCS3, BATF, MYC) that are associated with IL-6 pathway and known to be perturbed by tocilizumab treatment in rheumatoid arthritis patients." (PMID 35064122, 2022). "However, recent studies have shown that PIM1 plays a prominent role in immunoinflammatory diseases, including autoimmune uveitis, inflammatory bowel disease, asthma, and rheumatoid arthritis." (PMID 39372407, 2024). "Although PIM1 has been established to have a role in cancer progression, there is increasing evidence for wider pathological roles of PIM1 within the context of immunoinflammatory diseases, including Lupus nephritis (LN) and rheumatoid arthritis (RA)." (PMID 39372407, 2024). "Kaempferol has also been shown to prevent and treat inflammatory diseases such as rheumatoid arthritis and SLE by increasing FOXP3 expression in Treg cells or reducing PIM1-mediated FOXP3 phosphorylation at S422." (PMID 37026113, 2023).
asthma (4 papers, 2014 to 2024). "It has been revealed that pulmonary PIM1 concentrations are increased in mouse models of asthma after ovalbumin sensitization and challenge." (PMID 39372407, 2024). "Overall, the inhibition of PIM1 seems to be more beneficial than harmful in treating asthma." (PMID 39372407, 2024). "Targeting PIM1 may be effective in preventing the development of airway hyperresponsiveness, airway inflammation, and cytokine production in patients with asthma." (PMID 39372407, 2024). "The expression of PIM1 is not clear in patients with some immunoinflammatory diseases, such as IBD and asthma." (PMID 39372407, 2024).
bladder cancer (4 papers, 2010 to 2024). "Taken together, Pim-1 may be associated with bladder cancer initiation and progression." (PMID 21143989, 2010). "There is also evidence that downregulation of PIM-1 activity increased sensitivity to chemotherapy in the colon or bladder carcinoma cell lines." (PMID 34993612, 2022). "Several studies have demonstrated that Pim-1 kinase play a role in different cancer types, however, the function of Pim-1 in bladder cancer is poorly understood." (PMID 21143989, 2010). "The data shows that the staining intensity of Pim-1 is increased in invasive bladder carcinoma samples (95%) when compared with Non-invasive bladder cancer specimens (76%)(p < 0.01)." (PMID 21143989, 2010). "Since Pim-1 is also involved in bladder cancer cell survival and drug resistance, Pim-1 is a potential candidate for targeted therapy in bladder cancer." (PMID 21143989, 2010). "When compared with normal epithelium, Pim-1 was overexpressed in bladder cancer epithelium, and the expression level was higher in invasive bladder cancer than Non-invasive bladder cancer specimens." (PMID 21143989, 2010). "In order to further demonstrate the role and function of Pim-1 in bladder cancer, the expression level of Pim-1 was validated in bladder cancer cell lines using western blot." (PMID 21143989, 2010). "Pim-1 is expressed in all five bladder cancer cell lines at variable levels, with the maximum level in highly invasive cancer cell lines T24 and UM-UC-3." (PMID 21143989, 2010). "The localization of Pim-1 in bladder cancer cells was confirmed by immunoperoxidase staining and as the results showed that Pim-1 was detected in all human bladder cell lines examined, including T24, UM-UC-3, 5637, J82 and RT-4." (PMID 21143989, 2010). "In the present study we demonstrated for the first time that, Pim-1 was increased in human bladder cancer epithelium as compared with that in normal bladder tissue." (PMID 21143989, 2010). "Moreover, the knockdown of Pim-1 significantly inhibited bladder cancer cell growth and also sensitized cells to chemotherapeutic drugs in vitro." (PMID 21143989, 2010). "In this regard, Pim-1 might be one of the potential therapeutic targets for the treatment of bladder cancer and further studies examining Pim-1 as a target of therapeutics are worthy of investigation." (PMID 21143989, 2010). "Pim-1 was also detected in all the bladder cancer cell lines examined in our study." (PMID 21143989, 2010). "Therefore, the aims of the present study are to investigate the expression level of Pim-1 in bladder cancer tissue and study its function in the pathogenesis and progression of bladder cancer." (PMID 21143989, 2010). "Furthermore, downregulation of Pim-1 inhibited the bladder cancer cells growth and sensitized them to chemotherapy in vitro." (PMID 21143989, 2010). "As Pim-1 is involved in drug resistance in some cancer types and adjuvant intravesical chemotherapy is one of the most common treatments in bladder cancer, we tested whether Pim-1 is also involved in drug response of bladder cancer cells." (PMID 21143989, 2010). "Our results in this study suggest that Pim-1 may play a role in bladder cancer initiation and progression." (PMID 21143989, 2010). "Pim-1 was also detected in all human bladder cancer cell lines tested in our study." (PMID 21143989, 2010). "The current study offers significant information on the role and functions of Pim-1 in bladder cancer, and may aid in the development of novel therapy." (PMID 21143989, 2010). "Our data implied that Pim-1 may contribute to the resistance of apoptosis and survival of bladder cancer cells in response to cytotoxic drugs." (PMID 21143989, 2010). "Furthermore, downregulation of Pim-1 could also inhibit the cell growth and proliferation in vitro, suggesting that Pim-1 may be important for the growth and survival of bladder cancer cells." (PMID 21143989, 2010).